CLDN5 (claudin 5)
Diseases named in the same sentence as CLDN5 in open-access papers (continued):
Sharing a sentence is not in itself a finding about the gene and the disease.
psychiatric disorder (15 papers, 2019 to 2025). A disorder characterized by behavioral and/or psychological abnormalities, often accompanied by physical symptoms. "Added to this, a further decline of CLDN5 expression greatly increases the risk of psychiatric disorders like Cldn5 KD mice." (PMID 36978081, 2023). "Dysfunction of claudin-5 protein is associated with either neurodegenerative, neuroinflammatory, or psychiatric disorders, and with CNS bacterial infections." (PMID 34529552, 2021). "However, our results are more convincing as many studies show that decreased tight junction proteins are associated with mental illness, as in a study using experimental animals, rats subjected to prolonged stress showed decreased Claudin-5 levels and diminished function in TJs in vascular tissues." (PMID 39592970, 2024). "Claudin-5 has been studied in psychiatric disorders such as schizophrenia, bipolar disorder, obsessive–compulsive disorder (OCD), attention-deficit/hyperactivity disorder, and autism spectrum disorder, with inconsistencies across studies." (PMID 41458033, 2025). "Recent studies demonstrated the association between BBB disruption based on changes in the TJ proteins of the cerebral vascular endothelium and the development of psychiatric disorders, with claudin-5 and -12 being considered as the main targets." (PMID 38203447, 2023). "We also show that levels of tight junction mRNA transcripts, including claudin-5, claudin-12 and ZO-1 correlate with disease duration and age of onset of a range of psychiatric disorders." (PMID 33139732, 2020). "Taken together, these data clearly show that translational suppression and accumulation of CLDN-5 mRNAs by attenuation of PUM1 expression, loss of cytosolic PUM1 and/or PUMs-containing stress granules in larger vessels can be associated in a subset of psychiatric disorders." (PMID 38898501, 2024). "CLDN-5 expression levels were not related with the duration of psychiatric disorders, but they were negatively correlated with PUM1 levels (spearman r =-0.3831) and positively correlated with PUM2 levels (spearman r = 0.6030)." (PMID 38898501, 2024). "Although patients with MS or these psychiatric disorders were excluded from this study, plasma CLDN-5 levels should be investigated in patients with AD and other central nervous system-related diseases in order to understand the clinical utility of plasma CLDN-5 levels." (PMID 38338697, 2024).
neurodegenerative disease (9 papers, 2018 to 2026). A disorder of the central nervous system characterized by gradual and progressive loss of neural tissue and neurologic function. "In addition to the observed cerebrovascular changes, 5xFAD mice show lower levels of claudin-5, one of the most abundantly expressed tight junction proteins in the CNS, whose deficiency has been demonstrated to contribute to neurodegenerative disease progression as in AD." (PMID 41515287, 2026). "Thus, restoring claudin-5 function via TWEAK inhibition could serve as a potential therapeutic solution for multiple neurodegenerative diseases, and MS in particular." (PMID 36292599, 2022). "Claudin-5 expression was downregulated, consistent with the enhanced leakiness of the BCSFB encountered in neurodegenerative diseases and pathophysiology models." (PMID 29848382, 2018).
adenocarcinoma (3 papers, 2011 to 2017). A common cancer characterized by the presence of malignant glandular cells. "Compared to bronchial cells claudins 1, 3 and 4 and 7 were decreased and claudin 5 mRNA increased in adenocarcinoma while when compared to lung parenchyma claudin 4 mRNA was increased but claudin 5 decreased." (PMID 21619599, 2011).
bacterial infection (2 papers, 2022 to 2026). "An in vitro BBB model was constructed using a brain microvascular endothelial monolayer to examine the effects of bacterial infection on the expression of tight junction proteins (occludin, Claudin-5, ZO-1)." (PMID 41987901, 2026).
inflammation (2 papers, 2023). Aberrant reaction of the microcirculation characterized by movement of fluid and leukocytes from the blood into extravascular tissues. "UUO mice also demonstrated kidney vascular inflammation with elevated expression of adhesion molecules ICAM and VCAM and a leaky endothelial barrier with elevation in claudin-5 and VE-cadherin." (PMID 38235144, 2023).
kidney (2 papers, 2021 to 2022). "By investigating CLDN5 expression in DOCA‐treated unilateral nephrectomy mice, we could confirm CLDN5 recruitment to effaced FS areas as a general mechanism of murine kidney injury, rather than an NTS‐specific phenomenon." (PMID 34156149, 2021).
retinopathies (2 papers, 2023 to 2024). "However, the spatial co-distribution patterns of GNAZ, ADAM17, and CLDN5 in endothelial cells partially confirmed the susceptibility of retinal endothelial cells to blue light as well as the role of retinal endothelial cells in blue-light-mediated retinopathy." (PMID 37095509, 2023). "In a recent study, we reported that Cldn5 is upregulated in human retinal endothelial cells upon treatment with high glucose and advanced glycation end-products, and in an oxygen-induced retinopathy model in mice." (PMID 39335566, 2024). "The potential significance of Claudin-5 (Cldn5), a predominant endothelial tight junction protein in the pathogenesis of retinopathies, is underscored by our recent findings in vitro and in an experimental model of OIR." (PMID 39335566, 2024).
cardiovascular diseases (1 paper, 2023). "We tested the activity of the AMPK/mTOR signalling pathway, which is a potential target pathway of resistin in cardiovascular diseases, to further determine the molecular mechanism of H. parasuis-induced resistin in regulating claudin-5 and occludin expressions in PAECs." (PMID 36694280, 2023).
central nervous system diseases (1 paper, 2020). "Claudin-5 is considered to be a gatekeeper that is a key player in maintaining BBB homeostasis, and its expression is altered in various central nervous system diseases." (PMID 32912242, 2020).
kidney disease (1 paper, 2022). "Here the authors report that podocyte claudin-5 regulates WNT signaling activity by modulating WIF1 expression, and its downregulation contributes to kidney disease progression in mice." (PMID 35332151, 2022). "Our experiments also provide proof of principle that CLDN5 and WIF1 might be developed into therapeutic modalities for the treatment of kidney diseases affecting millions of people worldwide." (PMID 35332151, 2022).
vasculopathy (1 paper, 2022). "A hallmark of CAA vasculopathy is BBB hyperpermeability with altered expression of major TJ proteins, claudin-5, ZO-1, claudin-1, and occludin." (PMID 35813502, 2022).
CLDN5 also shares sentences with these, for which no sentence is quoted: brain diseases (3 papers); lung squamous cell carcinoma (3); mood disorder (3); cerebral oedema (2); glomerulopathies (2); lymph node metastasis (2); urothelial carcinoma (2); adenoma (1); age-related macular degeneration (1); alcohol abuse (1); amyotrophic lateral sclerosis (1); anaplastic astrocytoma (1); anthrax infection (1); aortic aneurysm (1); astrocytoma (1); benign vascular tumor (1); breast tumour (1); campylobacteriosis (1); cardiac arrest (1); chronic obstructive pulmonary disease (1); collagenous colitis (1); congenital heart disease (1); congenital heart malformation (1); coronary heart disease (1); deafness (1); delirium (1); demyelinating disease (1); ependymal tumor (1); erectile dysfunction (1); focal and segmental glomerulosclerosis (1).
A further 38 diseases each share a sentence with CLDN5 in 1 paper.